EPO (erythropoietin)
Diseases named in the same sentence as EPO in open-access papers (continued):
Sharing a sentence is not in itself a finding about the gene and the disease.
hepatocellular carcinoma (74 papers, 2007 to 2025). A malignant tumor that arises from hepatocytes. "The erythropoietin-producing hepatocellular carcinoma (Eph)A2 receptor is associated with increased vascular permeability; however, the developmental endothelial locus-1 (Del-1), has contrasting effects on endothelial function." (PMID 39926431, 2025). "Practically, a cDNA library from hepatoma cells, which have the oxygen-sensing system, would be transfected into a non-EPO-producing cell line containing a reporter gene linked to the EPO enhancer." (PMID 39833313, 2025). "Ratcliffe’s group used a hepatoma cell line known for its oxygen-sensitive EPO production and transfected these cells with variants of the EPO cDNA." (PMID 39833313, 2025). "Such five genes all encode the receptors for the erythropoietin-producing hepatoma amplified sequences (EPH), acting as the tyrosine-protein kinase receptor." (PMID 28255556, 2017). "EPO gene expression during hypoxia and the high expression levels observed in hepatoma cell lines have been classically associated with the activation of the transcription factor family HIFs, hypoxia-inducible factor." (PMID 23052842, 2013). "Interestingly, the critical association of VE-cadherin was determined with erythropoietin-producing hepatocellular carcinoma-A2 which in turn could engage the PI3K/Akt signaling pathway." (PMID 33663486, 2021). "The erythropoietin-producing hepatocellular carcinoma (Eph)A2 belongs to the largest family of receptor tyrosine kinases and significantly influences vascular formation and endothelial function." (PMID 39926431, 2025). "EPO has been discovered to have an immunosuppressive function in liver cancer (hepatocellular carcinoma, HCC)." (PMID 41012526, 2025). "In this study, we developed a new antibody targeting erythropoietin-producing hepatocellular carcinoma A2 (EphA2), which is highly expressed in NSCLC, and established CAR-T/ natural killer (NK) immune cells to verify its potential for immune cell therapy." (PMID 40181964, 2025). "In contrast, a human hepatoma cell line (Huh-7) was able to produce erythropoietin in significant levels with proper glycosylation due to its native cellular machinery." (PMID 39311373, 2024). "Eph receptors (erythropoietin-producing hepatocellular carcinoma), which constitute a large subgroup of the TKR family, play critical roles in interactions such as vascular development, cell migration and proliferation, and angiogenesis." (PMID 39329983, 2024). "In Hep3B human hepatoma cells, which upregulate EPO expression in response to hypoxia or cobalt, the induction of binding activity of HIF1a and EPO protein production are suppressed by Cd dose-dependently and without cell damage." (PMID 39256317, 2024). "Erythropoietin-producing hepatoma interactors (Ephrins) are transmembrane ligands for erythropoietin-producing hepatoma receptors (Ephs) tyrosine kinases." (PMID 39557830, 2024). "Potential new targets such as erythropoietin-producing hepatocellular carcinoma A2 (EphA2), tissue factor (TF), and protein tyrosine kinase 7 (PTK7) are currently under study in clinical trials." (PMID 37998743, 2023). "HIF-1 was first identified as a transcription factor regulating EPO in human hepatoma cells, while in vivo hypoxic stimulation of EPO and erythropoiesis is primarily mediated by HIF-2." (PMID 37430374, 2023). "Potential new targets such as erythropoietin-producing hepatocellular carcinoma A2 (EphA2), tissue factor (TF), and protein tyrosine kinase 7 (PTK7) are currently under investigation in clinical trials." (PMID 37998743, 2023). "Using hepatoma cell lines, the ~ 50-bp EPO 3′ hypoxia response element (HRE) has extensively been characterized." (PMID 35750861, 2022). "The erythropoietin-producing hepatocellular carcinoma (Eph) receptors constitute the largest sub-family of receptor tyrosine kinases (RTKs) identified until now." (PMID 35223830, 2022).
hepatocellular carcinoma (continued). "The erythropoietin-producing hepatocellular carcinoma (Eph) receptors and their Eph receptor-interacting (ephrin) ligands together constitute a vital cell communication system with diverse roles." (PMID 35223830, 2022). "Ephrins (erythropoietin-producing hepatocellular carcinoma) are the largest family of receptor tyrosine kinases known amongst mammals." (PMID 35891338, 2022). "Erythropoietin-producing human hepatocellular carcinoma (ephrin) receptors like Ephrin B2 are expressed by ECs and EPCs, and they are important for embryonic angiogenesis, cellular adhesion, and migration." (PMID 33627177, 2021). "Erythropoietin-producing human hepatocellular carcinoma (Eph) receptors, including types A (A1–A10) and B (B1–B6), are the largest subfamily of transmembrane receptor tyrosine kinases (RTKs)." (PMID 33880135, 2021). "Using proximity biotinylation assays, we identified SYK (spleen tyrosine kinase) as a kinase involved in DEPTOR Tyr 289 phosphorylation in an ephrin (erythropoietin-producing hepatocellular carcinoma) receptor–dependent manner." (PMID 34634301, 2021). "Erythropoietin-producing hepatocellular carcinoma (EPH) receptors are the largest family of receptor protein tyrosine kinase." (PMID 34634301, 2021). "Due to the lack of an appropriate renal cell culture system, the mechanisms of hypoxia-induced EPO expression were analyzed with the help of human hepatoma cells." (PMID 34209205, 2021). "Crosstalk between the AHR and hypoxia pathways was evident in a study, where endogenous AHR ligand suppressed nuclear accumulation of HIF2α and subsequent EPO production in human hepatoma HepG2 cells." (PMID 34209205, 2021). "The activation of the erythropoietin-producing hepatoma (EPH) receptor A2 (EphA2) is involved in FGF production." (PMID 32754598, 2020). "VE-cadherin induces erythropoietin-producing hepatocellular carcinoma-A2 (EphA2) to interact with its membrane bound ligand and become phosphorylated." (PMID 30915348, 2019). "EphA1, as the first member of the Eph receptor tyrosine kinase family, derives from erythropoietin‐producing hepatocellular carcinoma cell lines." (PMID 30873760, 2019). "A human genomic library was searched for gene sequences homologous to the tyrosine kinase domain of the viral oncogene v‐fps, which was overexpressed in an erythropoietin‐producing human hepatocellular carcinoma cell line (ETL‐1)." (PMID 30548122, 2019). "The erythropoietin-producing hepatocellular carcinoma (Eph) receptors are a cell-cell contact signaling pathway for regulating neuron function and death." (PMID 31469726, 2019). "The erythropoietin‐producing human hepatocellular carcinoma (Eph) receptors were first identified in 1987 during a search for tyrosine kinases involved in cancer." (PMID 30548122, 2019). "The human hepatoma cell lines Hep3B, which are so far the most prevalently used models for studying hypoxia-regulation of EPO expression in vitro, were utilized in our present study." (PMID 30108502, 2018). "It has not still been possible to separate and cultivate these different types of cells for a better study and thus, many studies about EPO synthesis regulation have been conducted with EPO‐producing hepatoma cells." (PMID 28857467, 2018). "The erythropoietin-producing hepatoma (EPH) receptor A2 (EphA2) belongs to the Eph family of receptor tyrosine kinases." (PMID 30451837, 2018). "For example, nuclear ACSS2 is essential for the lysine acetyltransferase CBP -mediated HIF-2α acetylation in human Hep3B hepatoma cells and in the erythropoietin (EPO)-generating organs of hypoxic or acutely anemic mice." (PMID 29991493, 2018). "The erythropoietin-producing hepatoma (EPH) family is the largest family of receptor tyrosine kinases, the dysfunction of which is recognized as a key initiator of carcinogenesis." (PMID 30451837, 2018).
hepatocellular carcinoma (continued). "The first member, named EphA1, was cloned from an erythropoietin-producing hepatocellular cancer cell line and the second member, EphA2, was identified by screening the human epithelial (Hela cells) cDNA library." (PMID 28752098, 2017). "The Eph family receptor-interacting (ephrin) ligands and erythropoietin-producing hepatocellular carcinoma (Eph) receptors constitute the largest known family of receptor tyrosine kinases." (PMID 26941654, 2016). "This is in agreement with other authors who showed that the erythropoietin/erythropoietin-receptor system is involved in angiogenesis in human hepatocellular carcinoma." (PMID 27543111, 2016). "The primary EPO producing organ is the kidney in adult mammal, while most of the knowledge of hypoxic EPO expression has been based on human hepatoma cell lines." (PMID 26557695, 2015). "Previous studies on melanoma have indicated that erythropoietin-producing hepatocellular carcinoma-A2 (EphA2), phosphoinositide 3-kinase (PI3K) and matrix metalloproteinases (MMPs) are the key factors for VM formation." (PMID 25202424, 2014). "Ephrin receptors were named Eph after the EPO-producing hepatocellular carcinoma cell line from which its cDNA was isolated." (PMID 25426117, 2014). "Our previous study demonstrated that inhibition of erythropoietin-producing hepatoma cell line-B2 (EphB2) expression resulted in the promotion of cancer growth, with EphB2 acting as a tumor suppressor in pancreatic cancer." (PMID 24959213, 2014). "EPO production has been reported in several diseases, including hepatocellular carcinoma, hemangioblastoma of the cerebellum, gastric and pancreatic cancer, and in kidney lesions, such as RCC, renal cysts and hemangioma." (PMID 25295086, 2014). "Our previous study showed that different pancreatic cancer cell lines with different levels of erythropoietin-producing hepatoma cell line-B2 (EphB2) expression exhibited different responses to QYHJ treatment." (PMID 24959213, 2014). "These include EPO-secreting tumours, such as renal cell carcinoma, hepatocellular carcinoma, and uterine leiomyomata, and following renal transplantation." (PMID 24312736, 2013). "The number of EPO gene transcripts in hepatoma and specifically in the human CC cell line Mz-Cha-2 increased significantly compared to normal hepatocytes." (PMID 23052842, 2013). "In line with this blood producing function, the application of FSS onto Hep3B human hepatocellular carcinoma cells induced the expression of EPO, a key regulator for erythropoiesis." (PMID 23284736, 2012). "With the trend to eliminate non-human constituent from biopharmaceutical products, as a preliminary approach, we have investigated the potential of human hepatoma cell line (Huh-7) to produce recombinant EPO." (PMID 22040235, 2011). "EPO is secreted in chronic hypoxia and EPO-secreting tumors including renal cell carcinoma, hepatocellular carcinoma, hemangioblastoma, pheochromocytoma and uterine myoma." (PMID 19946506, 2009). "In addition, desensitization of the oxygen-sensing mechanism in EPO-producing cells by uremic toxin indoxyl sulfate was demonstrated in human hepatoma cell line HepG2." (PMID 36855344, 2023). "In addition, recent findings suggest that CAR suppresses hepatocellular carcinoma through the erythropoietin signaling pathway in humans." (PMID 37746289, 2023). "That each of these three HRE-containing elements of the EPO locus confers hypoxia inducibility to a reporter gene has previously been shown in Hep3B hepatoma cells, but the same authors disputed the necessity of the 5′ HRE for hypoxic induction of Epo in the mouse kidney." (PMID 35750861, 2022). "Tumours with inappropriate EPO production and secondary erythrocytosis described in the literature are cerebellar hemangioblastomas, meningiomas, pheochromocytoma, uterine leiomyomas, parathyroid adenomas, hepatocellular carcinoma, and renal cell carcinoma." (PMID 34013406, 2021).
hepatocellular carcinoma (continued). "This experiment was designed to determine whether erythropoietin-producing human hepatocellular carcinoma (Eph) receptors were involved in the development of visceral pain." (PMID 33880135, 2021). "It was demonstrated that brucine inhibited vasculogenic mimicry which might be through the downregulation of erythropoietin-producing hepatocellular carcinoma-A2 and matrix metalloproteinase-2 and metalloproteinase-9." (PMID 30723742, 2019). "The prevalence of erythropoietin-producing tumors, which are mainly detected in renal cell carcinoma or hepatocellular carcinoma, is very low in secondary erythrocytosis; the prevalence of erythropoietin-producing uterine myoma is even lower, accounting for only 0.02–0.5% of all uterine myoma cases." (PMID 32025892, 2018). "In patients with gastric and hepatocellular carcinomas, the levels of EPO/EPOR correlate with angiogenesis and tumor progression; therefore, EPO might serve as an endogenous stimulant of vessel growth by an autocrine and/or paracrine loop." (PMID 28703764, 2017). "In addition, the level of Tyr-593-phosphorylated (activated) pro-apoptotic erythropoietin-producing human hepatocellular carcinoma receptor tyrosine kinase A2 (EphA2) increased after doxazosin treatment (50 μM) by 2.8±0.29-fold (n = 3; p = 0.048)." (PMID 24516604, 2014). "So far, the EPO/EpoR system has been indicated as playing a major angiogenetic role in murine models of hepatocarcinogenesis and in vitro studies have indicated the presence of mRNA and protein of both genes in HepG2 and Hep3B hepatoma cell lines." (PMID 23052842, 2013). "Unfortunately, the role of EPO/EPOR in hepatocellular carcinoma (HCC) progressing is still uncertain." (PMID 29238266, 2017). "In hepatocellular carcinoma, the downregulation of PADI2 inhibits EPO expression and promotes the proliferation and migration of hepatocellular carcinoma cells." (PMID 37020554, 2023). "To investigate resistance to TACE, we downloaded the expression data of EPO, HMOX1, and SERPINE1 in 25 hepatoma cell lines from the CCLE database and used our model to calculate the risk score of each cell line based on this transcriptomic data." (PMID 36213835, 2022). "As such, increased EPO production and erythrocytosis are demonstrated in patients with hepatocellular carcinoma and relatively increased EPOR expression with decreased EPO level by LPS treatment is possible." (PMID 34831360, 2021). "Polycythemia has been observed in patients with hepatocellular carcinoma (HCC) and is thought to result from the tumor’s secretion of erythropoietin." (PMID 32235007, 2020). "Furthermore, CCM downregulated the protein and mRNA expression of erythropoietin-producing hepatocellular carcinoma-A2, phosphoinositide 3-kinase and matrix metalloproteinase-2, indicating that CCM may function through these factors for the inhibition of VM formation." (PMID 25202424, 2014). "In Hep3B hepatoma cells, upstream stimulatory factor 2 (USF2), a basic helix-loop-helix-leucine-zip transcription factor, cooperates with HIF-2α to promote the hypoxic activation of HIF-2α target genes, including CITED2, EPO, and PAI-139." (PMID 30478339, 2018). "Importantly, EPO/EPOR levels correlated well with angiogenesis and progression of patients with hepatocellular carcinoma, neuroblastoma, squamous cell carcinoma of the tongue, melanoma, and gastric adenocarcinoma." (PMID 25426117, 2014). "In addition, in some types of cancer, such as renal cancer, hepatocellular carcinoma, or ovarian cancer, a non-compensatory increase in erythropoietin due to tumors can also lead to increased MCHC." (PMID 36350006, 2022).
malnutrition (72 papers, 2009 to 2025). Inadequate nutrition resulting from poor diet, malabsorption, or abnormal nutrient distribution. "Other potential causes of high RDW values are nutrition deficiency, erythrocyte fragmentation, and erythropoietin production dysfunction." (PMID 38541211, 2024). "RDW values have been shown to be impacted by several factors, such as malnutrition, bone marrow depression, erythropoietin use, thyroid dysfunction, iron or vitamin B12 deficiency, and cardiovascular disease." (PMID 36834895, 2023). "Low Hemoglobin levels also cause higher rates of NCI as it reflects poor immunity, malnutrition of the bone marrow and decreased red cell growth factors, such as erythropoietin, which have neuroprotective effects." (PMID 34348754, 2021). "Other studies have shown that low Hb in children with SCA is caused by reduced RBC life span (one-seventh of normal), low erythropoietin response and nutritional deficiency." (PMID 33214940, 2020). "The most common causes of EPO resistance, among other, are secondary hyperparathyroidism, chronic inflammatory processes, and malnutrition." (PMID 31412807, 2019). "Most factors causing EPO resistance are associated with malnutrition, chronic inflammation, hyperparathyroidism, and inadequate dialysis in HD patients, which shorten the lifespan of erythrocytes." (PMID 26788441, 2016). "After adjusting EPO levels by age, sex, malnutrition, hemoglobin and days of fever prior to visit/admission in the multivariate analysis, EPO only remained associated to Hb concentration (n = 149, p<0.001)." (PMID 21912616, 2011). "Moreover, OS, microinflammation, malnutrition, and vitamin D deficiency represent significant risk factors for developing resistance to long-acting EPO." (PMID 35464768, 2022). "These may include relative erythropoietin deficiency, erythropoietin resistance, malnutrition such as iron, folic acid, Vitamin B12 deficiency, or poor absorption of these substances due to gastrointestinal mucosal edema." (PMID 35581275, 2022). "Decreased erythropoietin production, nutrition deficiency, shortened red blood cell survival and increased iron losses might contribute to the lower hemoglobin levels in patients with reduced eGFR." (PMID 33740899, 2021). "Elevated EPO levels may be indicative of EPO resistance resulting from underlying co-morbidities including inflammation, iron status, malnutrition and disrupted NO metabolism." (PMID 32038269, 2019). "In the literature, higher serum ferritin has been proven to be associated with EPO resistance, malnutrition, and inflammation in dialysis patients, which could to a great extent explain the negative association between ferritin and mortality in our PD subjects and HD patients in previous literature." (PMID 40290139, 2025). "Inflammation is an important contributor to the development of malnutrition and erythropoietin resistance in hemodialyzed individuals." (PMID 36558477, 2022). "We believe that erythropoietin resistance index (ERI) can be used as an additional record while screening for malnutrition." (PMID 36558477, 2022). "Disturbed oxidative balance, microinflammation, malnutrition, vitamin D deficiency, and increased serum FER concentrations are significant risk factors for the development of EPO resistance in patients undergoing regular HD." (PMID 35464768, 2022). "The chronic inflammation evoked by cancer leads to inadequate production of erythropoietin, suppression of erythropoiesis, malnutrition, increased oxidative stress, and cachexia." (PMID 35205691, 2022). "Patients with heart failure had a greater degree of malnutrition–inflammation complex, and erythropoietin resistance." (PMID 34718902, 2021). "Patients with heart failure had significantly higher malnutrition inflammation scores and erythropoietin resistance indexes." (PMID 34718902, 2021).